IL6 (interleukin 6)
Diseases named in the same sentence as IL6 in open-access papers (continued):
Sharing a sentence is not in itself a finding about the gene and the disease.
colitis (continued). "In the Con-DSS group, the expression levels of pro-inflammatory cytokines (TNF-α, IL-6, and IFN-γ) and those of neutrophil-attracting chemokine CXCL2 were increased by colitis." (PMID 35688905, 2022). "In vivo murine studies revealed that KJK exposure increases the body weight and colon length, while reducing colonic epithelial injury, and the expression of inflammatory factors in colitis tissues such as TNF-α, IL-6, and IL-1β." (PMID 35774753, 2022). "Isolated from egg white proteins, MLGATSL, DEDTQAMPFR, DEDTQAMPF, and MSYSAGF significantly inhibited the IL-8 and TNF-α secretion and also down-regulated the mRNA expression of TNF-α, IL-17, IL-6, MCP-1, IL-1β, and IFN-γ in colitis mice." (PMID 35406093, 2022). "D-limonene demonstrated anti-inflammatory effects in colitis by decreasing cytokines (NF-κB, TNF-α, IL-1β, and IL-6) when administered orally in rats." (PMID 36432834, 2022). "Intriguingly, SPH treatment prevented a significant increase in pro-inflammatory TNF-α and IL-6 and additionally augmented the production of anti-inflammatory IL-10 and TGF-β1 compared with the other two colitis groups (p < 0.01)." (PMID 36139127, 2022). "Pro-inflammatory cytokines, including Il-6, IFN-α, and IL-1β, are the main characteristics of colitis." (PMID 36139747, 2022). "The study reported significant reduction in the serum level of IL-6 and TNF-α of LPS-induced, TNBS-induced colitis, and DSS-induced mice group." (PMID 36079752, 2022). "It suppressed the inflammatory response via the attenuation of TNF-α, IL-1β, IL-6, and MPO activity in colitis rats in TNBS-induced colitis." (PMID 36235004, 2022). "IL-6 production by lamina propria macrophages and CD4+ cells is increased in the experimental colitis and in IBD patients." (PMID 35832050, 2022). "Consistent with the elevated IL-6 production, 300 mg/kg PD significantly reduces the colon length shortening in the DSS-induced colitis mouse model." (PMID 35933374, 2022). "In the present study, the levels of IL-6, IL-17A, IL-1β, and TNF-α were increased, accompanied by increased expression of TLR5/MyD88/NF-κB pathway in TNBS induced colitis rats." (PMID 35571126, 2022). "Consistent with previous studies, our results indicated that GTP inhibited the activity of NF-κB and MPO, the expression of TNF-α, IL-1β, IL-6, iNOS, and COX-2, and the production of NO and PGE2 in colon tissues of mice with DSS-induced colitis." (PMID 35807865, 2022). "In vivo, DPG decreases the severity of DSS-induced colitis as well as intestinal inflammation reduction mediated by a downregulation of the pro-inflammatory cytokines TNF-α, IL-1β, and IL-6, as well as HMGB1 receptors, RAGE, and TLR4." (PMID 35456938, 2022). "Results showed that Shikonin dose-dependently alleviated mice colitis, down-regulated expression of F4/80, iNOS and CD86, decreased IFN-γ, IL-1β, IL-6 and TNF-α, while increased IL-10 in mice colon." (PMID 36059938, 2022). "The deficiency of CXCL13 resulted in significantly decreased expression of inflammatory cytokines IL-21, IL-1β, IL-1α, IL-17, IL-6 and TNF-α in colon sites of mice with colitis." (PMID 36172372, 2022). "Interleukin (IL)-6, TNF-α, and IL-12(P40), which have generally been recognized as pro-inflammatory factors in DSS-induced colitis, are activated by antigen-presenting cells to perturb the balance of helper T cells and regulatory T cells." (PMID 35935215, 2022). "A model of TNBS-induced colitis in DPP4-/- mice showed higher serum levels of neuropeptide Y (NPY), vasoactive intestinal peptide (VIP) and IL-6, which are all substrates of DPP4, compared to C57BL/6 mice." (PMID 35309368, 2022). "The mRNA expression levels of TNF-α, IL-6, and IL-1β in colon tissue of the DSS-induced colitis group were considerably elevated by the 4% DSS treatment." (PMID 36080669, 2022).
colitis (continued). "To further estimate the influence of MOP upon inflammation in colitis, we detected the levels of TNF-α, IL-1β, IL-6, and IL-10 in the serum from the control, DSS, and DSS + H MOP groups." (PMID 35911761, 2022). "Similar to human patients, murine colitis models show intense accumulation of Ly6Chi monocytes, which also produce high levels of IL-1β, TNF-α, IL-6, IL-12, and express high level of TREM1 and respond in a highly pro-inflammatory manner to TLR stimulation." (PMID 34912006, 2022). "We used qRT-PCR to examine the mRNA expression levels of pro-inflammatory cytokines, including TNF-α, IL-6, and IL-1β, in colon tissue because higher protein and mRNA levels of these cytokines were observed in the DSS-induced colitis animal model." (PMID 36080669, 2022). "During the pathogenesis of DSS-induced colitis, we investigated the expression of the proinflammatory cytokines IL-6, IL-1β, and TNF-α, which are abundantly recruited in mice during DSS-induced colitis." (PMID 36187993, 2022). "Cytokines, including IL-2, IL-6, and TNF-α, were measured in blood for cytokine profiling and to identify which cytokines best discriminate experimental colitis from controls." (PMID 35239781, 2022). "In colitis models, oral GDNPs 2 administration increased IEC survival and proliferation, decreased pro-inflammatory cytokines (TNF-α, IL-6, and IL-1), and increased anti-inflammatory cytokines (IL-10 and IL-22)." (PMID 36298592, 2022). "ANP downregulated TNF-α, IL-1β, IL-6, IFN-α, and IFN-β mRNA levels in the colonic tissue in the mouse model of colitis (P < 0.05)." (PMID 35280696, 2022). "As expected, the plasma levels of proinflammatory cytokines, including tumor necrosis factor alpha (TNF-α), interleukin (IL)-6, and IL-17, were significantly increased in the DSS-induced colitis model." (PMID 36009796, 2022). "B. vulgatus 7K1 ameliorated DSS-induced colitis in mice by decreasing the concentrations of TNF-α and IL-6 and increasing the production of IL-10 in mouse colon tissues." (PMID 36531989, 2022). "Colitis is characterized by abnormal levels of inflammatory cytokines, especially TNF-α, IL-6, and IL-1β." (PMID 35681301, 2022). "While A2BR signaling mediates glial upregulation of Il6 and downregulation of Csf3, Cxcl1, and Cxcl10, glial A2BRs in colon tissue mediated the DSS colitis-induced increase in protein expression of all these mediators." (PMID 35869148, 2022). "In our study, except for TNF-α, other pro-inflammatory factors such as IL-6 and IL-1β were also vastly increased in TNBS-induced colitis." (PMID 35571126, 2022). "β-myrcene was also effective in preventing the increase in proinflammatory mediators (COX-2 and iNOS) and cytokines (IL-6, IL-1β and TNF-α) at protein and mRNA expression levels and resulting in colitis remission." (PMID 36557879, 2022). "Further, the bovine and human MDEs attenuated the mucosal lesions, lymphocyte infiltration, colon shortening, and gene expression of pro-inflammatory cytokines (IL-6, TNF-α) in the DSS-colitis mice." (PMID 35399093, 2022). "There is a significant increase in IL-1β and IL-6 mRNA expression in the cortex and IL-1β and TNF-α in the hippocampus of mice with DSS-induced colitis." (PMID 34983592, 2022). "HHT alleviated DSS-induced colitis with downregulated TNF-α, IL-1β, IL-6, and CCL2 expression; reduced activation of nuclear factor-kappa B (NF-κB) signaling; and diminished proportion of recruited macrophages in colon tissues." (PMID 36211988, 2022). "In the present study, Latilactobacillus curvatus BYB3 (isolated from kimchi) significantly decreased the IL-6 and TNF-R1 levels and the disease activity index (DAI) during DSS-induced colitis in mice." (PMID 35001008, 2022). "In a chemical-induced mouse model of colitis, L. fermentum CQPC04 reduced TNF-α, IFN-γ, IL-1β, IL-6, and IL-12, and increased IL-10 release in serum; it also downregulated NF-kB and up-regulated IL-10 expression in colon tissue." (PMID 35408849, 2022).
colitis (continued). "Overactivity of pro-inflammatory factors such as IL-1β, IL-6, and TNF-α play important roles in inducing and maintaining colitis intestinal inflammation." (PMID 35645824, 2022). "One study found that IL-33 deficiency impaired the differentiation of ILC2 and Th17 cells, and reduced levels of cytokines such as IL-6 and IL-1, which protected mice against DSS-induced colitis." (PMID 35410210, 2022). "In the colon tissue or blood from DSS-induced colitis mice, the mRNA and protein levels of pro-inflammatory cytokines (TNF-α, IL-6, and IL-1 β) are enhanced." (PMID 36080669, 2022). "Our data suggest that pretreatment with Rg1 and ADSC + Rg1 markedly decreases the levels of TLR4 and MyD88, as well as the expression of TNF-α, IL-6, IL-1β, IFN-γ, and IL-17A in the DSS-induced mouse model of colitis." (PMID 35729638, 2022). "The expression of TNF-α, IL-6 and IL-1β was substantially upregulated in DSS-induced colitis mice, and treatment with PNU-282987 significantly reduced the enhancement." (PMID 36058917, 2022). "Conversely, overexpression of HIF-2α in intestinal epithelial cells lead to spontaneous DSS colitis in mice coinciding with an increased expression of TNF, IL-1β and IL-6, whilst deletion of HIF-2α in mice with DSS-induced colitis has a protective effect." (PMID 35769556, 2022). "Other studies demonstrated that colitis can increase the amounts of bacteria-derived toxic byproducts (LPS), pro-inflammatory cytokines (including TNF-α, IL-1β and IL-6), and gut leak." (PMID 36275694, 2022). "In this study, we determined that arbutin considerably downregulated the levels of inflammatory cytokines (IL-1β, IL-6, and TNF-α) and proteins (iNOS and COX-2) in colitis mice." (PMID 34594215, 2021). "Exposure to IS significantly induced colon shortening, myeloperoxidase activity, IL-1β, IL-6, and TNF-α expression, and NF-κB+/CD11c+ cell population in the colon, resulting in colitis." (PMID 33731795, 2021). "Olaparib reduced the inflammation score, the concentration of IL-1β and IL-6, enhanced the level of IL-10, and decreased the intestinal permeability in TNBS-colitis." (PMID 34567413, 2021). "We also found high red meat intake induced the production of more inflammatory cytokines such as IL-1β, TNF-α, IL-17, and IL-6 and inflammatory inducible enzymes such as COX-2 and iNOS in dextran sulfate sodium-induced colitis." (PMID 34355008, 2021). "It is reported that the tea extracts significantly decreased the production of proinflammatory cytokines (IL-6 and tumor necrosis factor-α (TNF-α))and increased the anti-inflammatory IL-10 in RAW264.7 macrophages and colitis mice." (PMID 34439208, 2021). "We found that treatment of both L.L-pMU45CR and L.L-pNU45CR reduced IL-6, IL-1β, and TNF-α expression, and restored IL-10 production which plays a regulatory role in colitis." (PMID 34650393, 2021). "Another flavonoid, myricetin, downregulates inflammatory factors including TNF-α, IL-6, IL-1β, NF-κB, p-NF-κB, PCNA, COX-2, and cyclin D1 in AOM/DSS-induced colitis in mice." (PMID 34950252, 2021). "G-CSF, GM-CSF, IL-6, IL-15, IP-10, KC, MIP-1α, and MIP-1β levels were increased in animals with colitis." (PMID 34916909, 2021). "In the sedentary colitis mice fed either SD or HFD, the mRNA expression of TNF-α, IL-1β and IL-6 was significantly increased compared with the respective values obtained in the group of non-exercising (sedentary) animals fed an SD (p < 0.05)." (PMID 33557311, 2021). "The transplantation of FBp, FBi, or FN mitigated IS-induced colitis in mice: they alleviated IS-induced myeloperoxidase and TNF-α and IL-6 expression in the colon." (PMID 33731795, 2021). "In intrarectal administration of TNBS-induced colonic inflammation model, EA at ST36 decreased TNF-α, IL-6, and IL-1β levels in plasma and MPO activities in colonic tissues." (PMID 35095910, 2021).
colitis (continued). "For example, in DSS-induced colitis, TpH1−/− mice produce lower levels of the pro-inflammatory cytokines TNF-α, IL-1β, and IL-6 and have reduced macrophage infiltration when compared to TpH1+/+ mice." (PMID 34502396, 2021). "Previously, reduced tissue MPO and plasma pro-inflammatory markers (TNF-α, IL-6) were also demonstrated in response to KYNA and SZR-72 treatments in experimental colitis." (PMID 34475875, 2021). "The Zingiberis Rhizoma decoction has been found to reduce colitis in mice by reducing the expression levels of TNF-α, IL-1β, IL-6, and IL-10." (PMID 34539797, 2021). "Cinacalcet also reduced production of the inflammatory cytokines TNFα, IL-1β, and IL-6 in the colon and sera of mice with DSS-induced colitis." (PMID 34880751, 2021). "Our results found that BL down-regulated the expressions of IL-1β, IL-6, and TNF-α inflammatory factors in the colon tissue of colitis mice and increased the expression levels of anti-inflammatory factors IL-10 and TGF-β." (PMID 33954162, 2021). "In another study that used DSS-induced acute colitis model, both LF EA (LEA) and HF EA (HEA) decreased the level of IL-1β, TNF-α, IL-6, and IL-12 in serum." (PMID 35095910, 2021). "In the dextran sulfate sodium (DSS)-induced colitis model, EA suppressed proinflammatory cytokines including IFN-γ, TNF-α, and IL-6." (PMID 35095910, 2021). "These include reductions in colitis symptoms, pro-inflammatory markers TNF-α, IL-1β, IL-6, MPO, and PGE2, and levels of NO and MDA, whereas TGF-β expression, GSH levels, and enzyme activities of SOD, CAT, GPx, and GR, were increased." (PMID 34073220, 2021). "In summary, LREE can regulate the IL-6 signaling pathway to modulate the balance of Th17 and Treg cells, thus attenuating DSS-induced colitis in mice." (PMID 34093175, 2021). "Our study found that TNF-a, IL-6, NO, MPO, and MPA levels increased in the colitis group and decreased after antioxidant therapy." (PMID 34912469, 2021). "Our results showed the expression levels of pIκB, NFκB p65 (phospho S536), IL-1β, IL-6 and TNF-α were increased in colitis mice." (PMID 34456904, 2021). "In accordance with other studies, we showed that colitis induction resulted in a significant increase in the level of proinflammatory cytokines (IL-1β, TNF-α, IL-6, and IFN-γ) and decreased the anti-inflammatory cytokine IL-10 in colon tissue." (PMID 33995942, 2021). "The production of proinflammatory mediators, including IL-1β, IL-6, TNF-α, IL-2, IL-17, and IFN-γ, plays a critical role in DSS-induced colitis in mice." (PMID 34804049, 2021). "Compared with the DSS induced colitis mice model group, administration of Schisandrin B more significantly reduced the serum TNF-α, IL-6, IL-18 and IL-1β levels in DSS induced colitis mice model." (PMID 34628369, 2021). "The level of IL-1β, IL-6, and TNF-α in the colon samples were found to be increased in response to the induction of colitis in mice, whereas, significantly reduced (p < .01) after CD–Cur–CANPs treatment." (PMID 34121560, 2021). "Feeding colitis rats with feed containing oat beta-glucans led to a reduction of high levels of CRP, Il-6, and Il-12 in the colon wall after 7 days." (PMID 33923129, 2021). "The mucosal immune system is activated during colitis, which is accompanied by increasing mRNA expression of pro-inflammatory cytokines, including tumor necrosis factor (TNF)-α, interleukin (IL)-1β, and IL-6." (PMID 34867926, 2021). "Oral administration of acacetin increased the production of iNOS, COX-2, IL-6, TNF-α and IL-1β in mice with DSS-induced colitis." (PMID 33806061, 2021). "Studies have reported that IL-6 and TNF-α levels are significantly increased in mice with DSS-induced colitis and that these components are involved in the regulation of signaling pathways such as apoptosis, migration, and protein synthesis." (PMID 34901119, 2021).
colitis (continued). "The present study confirmed and extended this effect by detecting a substantial reduction of IL-1α, IL-1β, IL-6, TNF-α, INF-γ, G-CSF, IL-13, GM-CSF, IL-3, MIP-1α, RANTES, and eotaxin cytokines in response to UTA77 treatment in both colitis models." (PMID 34497514, 2021). "Our laboratory has reported that ILK inhibition in a mouse model of colitis blocked NF-κB (IKK and p65) activation, and suppressed TNF-α, IL-6, and IL-1β production as well as infiltration of inflammatory cells." (PMID 34163519, 2021). "In the inflammatory phase of DSS-induced colitis, IL-1β, TNF-α and IL-6 mRNA expression were significantly increased in the colon." (PMID 34749758, 2021). "Levels of the pro-inflammatory cytokines IL-6 and tumor necrosis factor alpha (TNF-α) were higher in mice harboring P. intestinalis on day 7 of DSS colitis." (PMID 32433514, 2021). "The findings highlight that Otostegia fruticosa protects the severity and extent of colitis in rats by controlling the release of TNF-α and IL-6 as well as the antioxidant effect that resulted in mucosal protective effects." (PMID 33802553, 2021). "NF-κB and IL-6 and other inflammatory cytokines are also induced by ILK in experimental colitis and colorectal cancer." (PMID 34163519, 2021). "Inflammatory response plays a key role in activating the production of mature IL-6, IL-1β, and TNF-α in UC patients and colitis mice." (PMID 34867926, 2021). "A recent study showed that EGCG downregulated cytokine IL-6 and reduced the expression of STAT3 protein in the colon tissue of colitis-induced mice." (PMID 34068714, 2021). "HE ameliorated colitis in HFD mice by reducing colonic myeloperoxidase activity (by 2.3-fold), macrophage accumulation (by 2.6-fold) and mRNA expression of IL-6 (by 2.3-fold) in HFD mice." (PMID 34380504, 2021). "The phenotype named Colitis contains seven DEGs from our lists: IL10, IL11, IL1B, IL1RN, IL6, MIF and TNF." (PMID 34680872, 2021). "B. adolescentis IF1-03 has been shown to stimulate maturation of macrophages, producing higher levels of IL-10 and lower levels of IL-6 and TGF-β, features consistent with the upregulation of Treg cells in DSS-colitis mice in vivo and splenocytes in vitro." (PMID 33679767, 2021). "The levels of proinflammatory cytokines, including TNF-α, IL-6, interferon-γ (IFN-γ), interleukin-18 (IL-18) and interleukin-17a (IL-17a), were significantly increased in DSS-induced colitis mice (P < 0.05 vs. CON)." (PMID 34675239, 2021). "Oat β-glucan was shown to prevent DSS-induced colitis by downregulating the levels of TNF-α, IL-1β, IL-6, and iNOS." (PMID 35008842, 2021). "A previous study has demonstrated that the production of cytokines such as IL-1ɑ, IL-6, IL-10, and IFN-γ are significantly reduced in mice with enhanced STAT3 activity during DSS-induced colitis." (PMID 33673239, 2021). "After MSC-Exo treatment, the colon length in colitis mice increased; colon inflammatory injury decreased; TNF-α, IL-6, IL-1β, IL-17, and IL-18 levels decreased; and Claudin-1, ZO-1, and IκB levels increased." (PMID 34249964, 2021). "Ginsenoside Rh2 significantly decreased the expression of IL-6, TNF-α, and IFN-γ in mice with DSS-induced colitis." (PMID 33462754, 2021). "IL-6 production by lamina propria macrophages and CD4+ T cells was increased in experimental colitis and in patients with IBD." (PMID 33633749, 2021). "Many proinflammatory cytokines, such as IL-6, IL-1β, TNFα, and IL-17, are increased in DSS-induced colitis and UC patients." (PMID 34804049, 2021). "This is accompanied by lower production of colonic inflammatory cytokines (i.e., Nlrp3, IL-1β, IL-6, Tnf-α and Ccl2, all these are REV-ERBα target genes) in ZT10-treated than in ZT2-treated colitis mice." (PMID 34393786, 2021). "In a previous study, needle-based VNS decreased the plasma level of TNF-α and IL-6 in a rodent model of 2,4,6-trinitrobenzene sulfonic acid–induced (TNBS-induced) colitis by inhibiting proinflammatory cytokines via the autonomic mechanism." (PMID 34138761, 2021).